IL21 (interleukin 21)
Diseases named in the same sentence as IL21 in open-access papers (continued):
Sharing a sentence is not in itself a finding about the gene and the disease.
gastritis (5 papers, 2014 to 2024). Inflammation of the stomach. "Further, raised levels of IL-21 among H. pylori-positive patients suggest a possible role of Th17 cells in the immunopathogenesis of H. pylori-associated gastritis." (PMID 29391865, 2017). "Collectively, our findings expand the understanding of IL-21+TFH-like CD4+ T cells in H. pylori-positive gastritis and investigate the underlying regulatory mechanism, which may provide potential interventions in the clinical treatment of H. pylori-induced gastritis." (PMID 34589088, 2021). "Data showed that the percentage of IL-21+CD4+T cells was positively correlated with the frequency of B cells in the mucosa of H. pylori-positive gastritis patients." (PMID 34589088, 2021). "In the present study, we explored the regulatory role of the GITR/GITRL axis in facilitating mucosal TFH-like cell activation and IL-21 production in H. pylori-positive gastritis patients." (PMID 34589088, 2021). "We identified a class of TFH-like CD4+ T cells with the capacity to secrete IL-21 in the gastric mucosa of H. pylori-positive gastritis patients and demonstrated that the GITR/GITRL axis promoted IL-21+CD4+ T cell polarization via the STAT3 signal pathway." (PMID 34589088, 2021). "The results showed that the co-localization of IL-21 with CD4+ T cells in the gastric mucosa was increased in H. pylori-positive gastritis patients." (PMID 34589088, 2021). "Here we identified a subset of tissue-resident CXCR5-BTLA-PD-1hi TFH-like cells with IL-21 production in the mucosal tissue of H. pylori-positive gastritis patients." (PMID 34589088, 2021). "To fully elucidate the role of IL-21+TFH-like cells in H. pylori-positive gastritis, we next explored the regulatory role of IL-21+TFH-like cells in B cell function." (PMID 34589088, 2021). "To explore whether GITR facilitated IL-21 production by TFH-like cells in H. pylori-positive gastritis, we determined the alternation of IL-21 production after GITR intervention." (PMID 34589088, 2021). "Here we revealed the role of IL-21-producing TFH-like cells in H. pylori-positive gastritis." (PMID 34589088, 2021). "Taking these data together, we revealed that GITR/GITRL signal promoted the polarization of mucosal IL-21-producing CD4+T cells in H. pylori-positive gastritis, which may provide therapeutic strategies for the clinical treatment of H. pylori-induced gastritis." (PMID 34589088, 2021). "Furthermore, the blockage of IL-21 in the co-culture system inhibited B cell proliferation induced by CD4+T cells from H. pylori-positive gastritis patients." (PMID 34589088, 2021). "In addition, an increased percentage of IL-21+ CD4+T cells was detected in biopsy samples from H. pylori-positive gastritis patients." (PMID 34589088, 2021). "However, the regulatory mechanism of IL-21-producing T cells in H. pylori-infected gastritis remains unclear." (PMID 34589088, 2021). "We firstly analyzed the percentage of gastric CD19+B cells as well as the correlation between the percentage of IL-21+CD4+T cells and CD19+B cells in H. pylori-positive gastritis patients." (PMID 34589088, 2021). "Meanwhile, we identified glucocorticoid-induced tumor necrosis factor receptor (GITR) as an important regulator to facilitate IL-21 production by CD4+T cells and accelerate mucosal inflammation in gastritis patients with H. pylori infection." (PMID 34589088, 2021). "Taking these data together, we found that IL-21+ CD4+T cells were increased and exhibited TFH-like phenotype in H. pylori-positive gastritis patients compared to healthy controls." (PMID 34589088, 2021). "Here we identified an IL-21-producing gastric CD4+T cell subset, which exhibited tissue-resident CXCR5−BTLA−PD-1hi TFH-like phenotype in H. pylori-positive gastritis patients." (PMID 34589088, 2021). "Consistent with the increased percentage of IL-21-producing TFH-like cells, the expression of GITR was also elevated in mucosal CD4+T cells from H. pylori-positive gastritis patients." (PMID 34589088, 2021).
gastritis (continued). "Although the levels of IL-5, IL-6, IL-9, IL-10, IL-13, and IL-21 were higher in patients with gastritis than Hp- group, this increase was not significant." (PMID 39807418, 2024). "In conclusion, the significant elevation of IL-17 and IL-23 and high expression of IL-21 and TNF-α in the serum of H. pylori-positive patients further supports the role of Th-17 cells in the pathogenesis of H. pylori infection and the severity of gastritis." (PMID 29391865, 2017). "Other group also revealed that IL-21 regulates Th1 and Th17 effector responses during chronic H. pylori infection in a STAT1- and STAT3-dependent manner, therefore playing a major role controlling H. pylori infection and gastritis." (PMID 25349535, 2014). "Taking these data together, it is indicated that IL-21 produced by mucosal TFH-like cells promoted the production of pro-inflammatory cytokines and chemokines and facilitated the secretion of matrix metalloproteinases in gastric epithelial cells during H. pylori-positive gastritis." (PMID 34589088, 2021). "In patients with non-ulcer dyspepsia, gastritis or peptic ulcers that were infected by H. pylori, a high secretion of IL-17, IFN-γ, IL-23, IL-6, IL-10, TNF-α, IL-21, IL-8, and IL-37 was reported." (PMID 35955936, 2022).
Granuloma (5 papers, 2014 to 2021). A compact, organized collection of mature mononuclear phagocytes, which may be but is not necessarily accompanied by accessory features such as necrosis. "The findings suggested that IL-35 and IL-21 levels in the BALF of mouse models of sarcoidosis granuloma were elevated, and the proportions of Bregs and Tfh cells in the peripheral blood and BALF also increased, however the proportion of Tregs decreased." (PMID 32508842, 2020).
Hypertension (5 papers, 2012 to 2025). The presence of chronic increased pressure in the systemic arterial system. "In our study, the percentage of Th17 cells co-producing IL-21 and IL-22 was more than twice as high in patients with pregnancies complicated by hypertension as in healthy pregnant women; we also observed a weak positive correlation with maternal age." (PMID 41156157, 2025). "After the onset of hypertension, pharmacological inhibition of IL-21 lowers blood pressure, resolves endothelial dysfunction, and mitigates vascular inflammation." (PMID 38791032, 2024). "Aged subjects with hypertension and dyslipidemia were also similar in their induction of IL-21 (p>0.4)." (PMID 23064011, 2012). "This study suggests that targeting IL-21 or its producing cells may offer novel therapeutic strategies for treating hypertension and its microvascular and macrovascular complications." (PMID 38791032, 2024). "Importantly, human subjects with hypertension exhibit higher levels of IL-21 in their PBMCs compared to individuals with normal blood pressure." (PMID 38045685, 2023).
periodontal disease (5 papers, 2016 to 2026). "Further longitudinal studies are required to further characterize and determine the diagnostic value of IL-21 as a reliable biomarker in periodontal disease." (PMID 34104811, 2021). "Further longitudinal studies are required to characterize and determine the diagnostic value of IL-21 as a reliable biomarker in periodontal disease." (PMID 34104811, 2021). "Altogether, IL-21 exaggerates the host-immune response and intensifies the local inflammatory actions, and these data support an important role of IL-21 in the pathogenesis of periodontal disease." (PMID 26998377, 2016). "Only two studies showed significant correlation of IL-21 level with periodontal disease severity." (PMID 26998377, 2016). "The authors concluded, it is likely that elevated IL-6 reflects the degree of subclinical inflammation in periodontal tissues, which can be a link between periodontal disease and OSAS, and the presence or severity of OSAS does not affect the level of IL-1β and IL-21 in either plasma or saliva." (PMID 26998377, 2016).
sarcoidosis (5 papers, 2014 to 2022). Sarcoidosis is a multisystemic disorder of unknown cause characterized by the formation of immune granulomas in involved organs. "IL-17 elevated levels have been also described in the serum of sarcoidosis and IL-17/ IL-21 in birdshot chorioretinopathy and in Vogt-Koyanagi-Harada disease." (PMID 35061677, 2022). "A few studies have analyzed the roles of the Th17 effector cytokines IL-17A/F, IL-21, and IL-22 in the pathogenesis of sarcoidosis." (PMID 26845566, 2016). "In skin lesions of sarcoidosis patients, IL-21 has been found to be elevated, whereas IL-17 and IL-22 were not dysregulated." (PMID 25386143, 2014). "A few studies have analyzed the role of the Th17 effector cytokines IL-17A/F, IL-21, and IL-22 in sarcoidosis, but the results are contradictory." (PMID 25386143, 2014). "Compatible with this hypothesis we found an expansion of TFH1 cells within the BALF compared to sarcoidosis significantly correlating with the expansion of CD21low B cells, prone to provide both IFNγ and IL-21 co-stimulation." (PMID 33613543, 2020).
schizophrenia (5 papers, 2022 to 2025). A major psychotic disorder characterized by abnormalities in the perception or expression of reality. "In addition, proinflammatory cytokines produced by pathogenic Th17 cells, such as IL-17 and IL-21, have a significant role in the onset and progression of schizophrenia." (PMID 36256663, 2022). "We recently created a novel neuroimmunotoxic pathway index in schizophrenia, particularly deficit schizophrenia, by connecting IL-6, IL-23, and IL-17 to critical actors such as IL-21, IL-22, and TNF-α." (PMID 36429996, 2022). "IL-1β, IL-22, G-CSF, IL-21, and IL-10 were significantly higher in schizophrenia than in controls." (PMID 36256663, 2022). "By inference, the strong effects of the IL-6/IL-23/Th17 axis on both the cognitive detrioration and symptomatome of schizophrenia indicate that IL-23, Th17, IL-22 and IL-21 may further contribute to the neurotoxic effects." (PMID 36256663, 2022). "The first major finding of this study is that IL-23, IL-6, IL-17, and TNF-α were considerably greater in MNP than in SNP, while IL-1β, IL-22, G-CSF, IL-21, IL-17, IL-10, and TNF-α were significantly higher in schizophrenia than in controls." (PMID 36256663, 2022). "This study aimed to examine serum levels of Th17-related cytokines (IL-17, IL-21, IL-22, IL-23) and chemokines (CCL2, CCL5, CCL20, CXCL10, IL-8) in schizophrenia patients compared to healthy controls and to explore their associations with symptom severity and laboratory parameters." (PMID 41200225, 2025). "The present study compares the serum levels of selected cytokines and chemokines—IL-17, IL-22, IL-23, IL-8, IL-21, CCL20, CXCL10, CCL2and CCL5—in schizophrenia patients to healthy controls due to growing evidence linking immune-inflammatory and metabolic dysregulation to schizophrenia." (PMID 41200225, 2025). "Here, we analyzed changes in serum concentrations of cytokines (IL-1β, IL-2, IL-4, IL-6, IL-10, IL-21, APRIL, BAFF, PBEF/Visfatin, IFN-α, and TNF-α) and growth/neurotrophic factors (GM-CSF, NRG1-β1, NGF-β, and GDNF) in patients with schizophrenia in an exacerbation phase." (PMID 37239308, 2023). "Furthermore, increased levels of IL-1β, IL-6, IL-17, IL-21, IL-22, IL-23, and tumor necrosis factor (TNF)-α were all found to be inversely related to HR-QoL in these schizophrenia patients." (PMID 36011997, 2022). "Nevertheless, there is no data on whether the IL-6, IL-23, and Th17 (IL-17, TNF-α, IL-21 and IL-22) axis is more associated with MNP than with SNP and whether changes in this axis are associated with the G-CoDe and the phenome of schizophrenia." (PMID 36256663, 2022).
Sepsis (5 papers, 2011 to 2024). Sepsis is defined as life-threatening organ dysfunction caused by a dysregulated host response to infection. "We observed deficiencies in the IL-23-Th17 axis and the IL-21 expression in these patients, which may characterize aspects of immunosuppression in those progressing to sepsis." (PMID 28769538, 2017). "Following induction of CLP-induced sepsis, increased IL-21 production was indicative of increased functionality in CD4+ TFH cells, which in turn were able to reverse the sepsis-induced decline in splenic B cells seen in controls." (PMID 38197178, 2024). "Mean cytokine level of IL1A, IL12, IL21, IL23 was increased in survivors of sepsis." (PMID 33667236, 2021). "The other cytokines in our study (IL-1β, TNF-α, IL-12/23p40, IL-21, IL-17, G-CSF, and GM-CSF) do not appear to be useful markers for clinical decisions regarding sepsis." (PMID 28769538, 2017). "Moreover, in the late phase of AP, IL-21 levels are elevated in septic patients with SAP and in patients with pancreatic necrosis, which suggests a potential role of IL-21 in AP with necrosis and sepsis." (PMID 32296650, 2020). "Using a well-established qRT-PCR protocol we could not find any detectable IL-21 mRNA in PBL's of humans with sepsis, suggesting that IL-21 is predominantly produced by lymphocytes populations other than PBL's and is not of pivotal importance in the immune response to infection in adults." (PMID 21711552, 2011).
vitiligo (5 papers, 2016 to 2024). Generalized well circumscribed patches of leukoderma that are generally distributed over symmetric body locations and is due to autoimmune destruction of melanocytes. "Elevation of IL21 further argues for T cell activation in the target tissue at this stage of vitiligo development." (PMID 38720888, 2024). "IL-21 is upregulated in vitiligo of SLCs, and increased serum levels have been detected in vitiligo patients with a positive correlation with BSA." (PMID 34768860, 2021). "IL21, which has previously been reported to be upregulated in the Smyth chicken line, another model of spontaneous vitiligo, was unchanged in our samples." (PMID 33384688, 2020). "Highly significant changes in the expression of T cell activation-related genes IFNG, FASLG, GZMA and IL21 and anti-inflammatory genes IL10 and TGFB1 were found in growing feathers of vitiligo-expressing Smyth chickens (P < 0.0001)." (PMID 38720888, 2024). "Curiously, while IL-21 was detected in our study, its levels in the target tissue did not increase until much closer to vitiligo onset." (PMID 38720888, 2024). "In addition to the expression of immunoregulatory genes prior to vitiligo onset in Smyth chickens, we observed a steady increase in IL21R expression, the receptor for IL-21." (PMID 38720888, 2024). "The relative expression levels (fold change) of IFN-γ, IL-10, and IL-21, which were designated as the signature cytokines in SLV, were, however different in eyes and GF with active vitiligo (140, 15, and 30 in SL-IV eyes and 20, 37, and 38 in GF, respectively)." (PMID 35547230, 2022). "Other groups have reported that IL10, IL13, IL17A, and IL21 are increased in vitiligo, though we did not observe this in our case series study." (PMID 33384688, 2020).
acute myeloid leukemia (4 papers, 2019 to 2024). Acute myeloid leukemia (AML) is a group of neoplasms arising from precursor cells committed to the myeloid cell-line differentiation. "In a phase I clinical trial, 12 patients with refractory acute myeloid leukemia were administrated with expanded high dose of NK-cells (106-107/kg/dose) using membrane-bound IL-21 and CD137 ligand expressed on K562." (PMID 39462383, 2024).
autoimmune hepatitis (4 papers, 2017 to 2025). Hepatitis caused by autoantibodies. "Some studies have focused on the contribution of IL-21 to inflammatory disease such as autoimmune hepatitis, rheumatoid arthritis." (PMID 29192177, 2017). "In patients with untreated autoimmune hepatitis (AIH), circulating B-cell activating factor of the tumour necrosis family (BAFF), IL-21, and B-cell populations were determined." (PMID 35368991, 2022).
chronic GVHD (4 papers, 2018 to 2024). "Anti-IL21 therapy was succesful to treat bronchiolitis obliterans in a mouse model of chronic graft-versus-host disease, whereas depletion of anti-CD20 therapy failed." (PMID 38384450, 2024). "However the proportion of CD4+ T cells generating cytokines, such as TNF-α, TGF-β, IL-21 and IL-13, which are critically involved in chronic GVHD, was significantly reduced in mLN from CpG-proB recipients, while only IL-13-expressing CD4+ T cells were diminished in pLN." (PMID 35479094, 2022). "In chronic GVHD (cGVHD), donor T cells may differentiate into IL-21 producing T follicular helper cells or tissue resident T helper cells that cooperate with germinal center B cells or memory B cells, respectively, to produce allo- and auto-reactive antibodies with subsequent tissue fibrosis." (PMID 34712243, 2021).
Cirrhosis (4 papers, 2014 to 2023). A chronic disorder of the liver in which liver tissue becomes scarred and is partially replaced by regenerative nodules and fibrotic tissue resulting in loss of liver function. "The results showed that serum IL-21 levels in the CHB and HB-ACLF groups were higher than in patients with cirrhosis caused by HBV infection." (PMID 24669269, 2014). "CD4+IL-21+ T cell frequency in the CHB group was higher compared with the cirrhosis group and correlated with the peripheral blood lymphocyte counts." (PMID 24669269, 2014). "In addition to Th17 cells, an elevated frequency of IL-21+CD4+ cells and increased expression levels of IL-21 have been discovered in CHB patients with cirrhosis." (PMID 37041599, 2023). "In addition, these splenic Tfh cells are largely expanded and produced more IL-21 in LC patients than those from HC subjects regardless of cirrhosis-associated etiology." (PMID 31456809, 2019). "The frequency of IL-21+CD4+ T cells in the CHB, HB-ACLF and cirrhosis groups was significantly higher compared with the HC group (P<0.05)." (PMID 24669269, 2014). "The mean serum level of IL-21 in the CHB group was 303.54±152.77 ng/ml, which was higher compared with that of the cirrhosis and HC groups." (PMID 24669269, 2014). "The mean serum level of IL-21 in the HB-ACLF group was 455.38±412.38 ng/ml, which was significantly higher than that of the CHB, cirrhosis and HC groups." (PMID 24669269, 2014). "IL-21 levels were measured in patients with CHB, HB-ACLF and cirrhosis over time." (PMID 24669269, 2014).
coronary artery disease (4 papers, 2016 to 2020). "An in vitro co-culture revealed a significant increase in the expression of INF-γ, IL-17, and IL-21 in coronary heart disease patients, and an increase in the expression level of B cell inflammatory genes." (PMID 33614738, 2020). "Our results show a negative correlation between plasma levels of IL-21 and Foxp3 and a positive correlation between plasma ApoAI and Treg and in human samples obtained from patients with coronary artery disease, indicating that our findings in atherosclerotic mouse models have relevance in humans." (PMID 29545616, 2018).
dengue (4 papers, 2017 to 2023). "On evaluating the cytokine function of the TFH CD4+ T cells in DSV4 immunized mice, we found that dengue EDIII 1-4 peptide pool stimulation resulted in a significantly higher proportion of IL-21+ and IL-10+ TFH CD4+ T cells." (PMID 36926350, 2023). "The frequency of IL-21 producing Tfh cells were highly significant (p < 0.0001) in patients with acute dengue when compared with healthy individuals, where hardly any cytokine production was observed." (PMID 32264870, 2020). "Both Epstein-Barr Virus and Dengue virus infections have shown delays in IL-21 levels that rise past seven days into the infection." (PMID 28427414, 2017). "Therefore, in order to investigate the cytokine production potential of Tfh cells in acute dengue, we sought to determine IL-21 production by the Tfh cells in patients with acute dengue ex vivo." (PMID 32264870, 2020).